IL10 (interleukin 10)
Diseases named in the same sentence as IL10 in open-access papers (continued):
Sharing a sentence is not in itself a finding about the gene and the disease.
colitis (continued). "Germ-free IL-10 knockout mice transplanted with gut microbiota from pediatric UC patient fecal samples, which are prone to spontaneous colitis, were used in this study." (PMID 39683625, 2024). "Curcumin treatment significantly reduced pro-inflammatory cytokines IL-1, IL-6, and CCL-2 in the colon tissue of colitis mice, while increasing anti-inflammatory cytokines IL-33 and IL-10." (PMID 39411430, 2024). "A growing body of research suggests a protective role for IL-10 in colitis induced by a variety of factors, particularly in the prevention of inflammatory bowel disease (IBD)." (PMID 39591319, 2024). "N. brasiliensis‐derived EVs were used as treatment in a mouse model of chemical‐induced colitis and demonstrated to reduce IL‐6, IL‐1β, IFNγ and IL‐17a and increase IL‐10 expression." (PMID 39113589, 2024). "Exosomes from DCs (DC-Exos) treated with IL-10 upregulate the levels of Tregs in the colonic lamina propria and attenuate colitis in a mouse model." (PMID 38255819, 2024). "Taken together, these data indicate that in conditions of impaired Foxp3+ IL-10 production, intestinal Tr1 cells expand in frequency and function to provide functional immune suppression and protect against spontaneous colitis." (PMID 37314833, 2023). "To better understand the role of Foxp3-specific IL-10 in protecting against colitis, we tracked changes in body weight among Foxp3-specific IL-10cKO mice during a 30-wk time course." (PMID 37314833, 2023). "Ligliptin activated the AMPK-SIRT1-PGC-1α pathway and inhibited the JAK2/STAT3 signaling pathway, downregulated TNF-α, IL-6 and NF-κB p65, and upregulated the anti-inflammatory cytokine IL-10, reducing the severity of colitis." (PMID 37483618, 2023). "As shown, increased proportions of Th1 and Th17 T cells and decreased proportions of Treg and IL‐10+ T cells were observed in mYthdc1−/− mice under colitis conditions, so did cytokines levels in colonic mucosae." (PMID 36922750, 2023). "Flow cytometric analysis revealed that IL-10-producing macrophages observed in the colonic LP of sham-treated mice were M2 macrophages and that percentage of colonic IL-10-producing M2 macrophages decreased with the development of colitis." (PMID 38012544, 2023). "In the TNBS colitis prevention trial, Hif1a and Tgfb1 expression was elevated by MTADV as in the therapeutic trial, but it also caused an increase in Tnfa, Vegfa, and Il10." (PMID 37047397, 2023). "As both WT and IL-10−/− a similar amount of food and drink and the drop-off in weight corresponds with the development of colitis, we attribute the weight changes to catabolism from the inflammatory bowel disease." (PMID 36869359, 2023). "Development of spontaneous intestinal inflammation is a complex process involving innate and adaptive immune responses, and the critical role of Th1/Th17 cells has been described in the Il10−/− colitis model in conventional/SPF settings." (PMID 36993463, 2023). "In one past study, Aquamin® was reported to reduce symptoms of colitis in the 25-week IL-10−/− mouse model." (PMID 37476158, 2023). "IL-10-deficient animals are particularly susceptible to experimental colitis, and single-nucleotide polymorphisms at the IL-10 locus are associated with early-onset colitis, suggesting that homeostatic IL-10 signaling may be essential for maintaining barrier function." (PMID 36696569, 2023). "Previous studies have shown that 17 strains of clostridium from healthy human microbiota can induce the production of IL-10, thus inhibiting colitis." (PMID 36902386, 2023). "Intestinal microbiota is required for colitis initiation and development in mice treated with dextran sodium sulfate (DSS)-treated mice or deficient in IL-10." (PMID 37813835, 2023). "The role of OPN in the development of colitis showed that the enteric bacterial profile of OPN/IL-10 double knock-out mice is distinctly different from that of IL-10 KO mice, indicating that OPN expression in enteric epithelial cells affects the microbiota." (PMID 37299387, 2023).
colitis (continued). "Odoribacter splanchnicus protect against colitis and colon cancer by inducing intestinal Th17 cells, and showing an anti-inflammatory activity by inducing IL-10 production." (PMID 37228621, 2023). "Previously, therapeutic effects of MSCs through THBS1-mediated induction of IL-10-producing B cells were shown on colitis." (PMID 37122871, 2023). "Within B cells, stabilization of HIF under hypoxic conditions results in the induction of IL-10 transcript and secretion of IL-10 into the inflammatory microenvironment which promotes resolution of experimental colitis." (PMID 36742292, 2023). "Quercetin, a flavonoid with antioxidant properties, can potentially reduce TNF-α levels and increase IL-10 levels in C. rodentium-induced experimental colitis models." (PMID 37465689, 2023). "Alloprevotella has been reported to be a SCFA-producing bacterium, and its abundance was positively correlated with the IL-10 level in a mouse model of dextran sodium sulfate-induced colitis." (PMID 37737162, 2023). "Parasutterella has a positive correlation with butyrate and IL-10, indicating that it can relieve colitis by altering the metabolic products of microbes." (PMID 37047694, 2023). "Our results suggest that IL-10 expression in patients with extensive colitis is significantly higher than that in patients with distal colitis when disease activity is similar between the two groups." (PMID 37457023, 2023). "Meanwhile, the secretion of proinflammatory factors IL-1β, IL-6, TNF-α, and PGE2 was enhanced, as well as the levels of anti-inflammatory factor IL-10 were reduced in the serum of colitis rats, which was all reversed by EA treatment." (PMID 36910013, 2023). "Studies on Ac-AIP-1 in a TNBS colitis model show suppression of colon IL-10, TGF-β and TSLP and Treg cell accumulation, making the protein a novel therapeutic candidate for inflammatory bowel disease treatment." (PMID 36883013, 2023). "Given that monocytes are the main source of IL‐10 production, we used Il10−/− mice developing colitis spontaneously for further investigation." (PMID 36922750, 2023). "-Attenuated severity of colitis.-Decreased colonic MPO activity.-Normalized IL-10 level in colon.-Anti-inflammatory changes in a GPR109a-dependent manner." (PMID 37447318, 2023). "Despite the extensive utilization of IL-10−/− mice as a model of experimental colitis in research, there is a need to further investigate and explore the sex differences in the IL-10 anti-inflammatory pathway response and their impact on the microbiota." (PMID 37373511, 2023). "Further studies have shown that Hpb colonization protects mice from TNBS-induced colitis while upregulating the Th2-associated cytokines, IL4, IL5, and IL13, and the regulatory cytokine, IL10." (PMID 37189818, 2023). "Taken together, these data suggest that adipose tissues from adipocyte autophagy‐deficient mice have an impaired production and secretion of anti‐inflammatory IL‐10 in DSS‐induced colitis compared to wild‐type mice." (PMID 36795015, 2023). "Next, we investigated the effects of the small-molecule inhibitors targeting NLRP3 (MCC950) and Caspase-8 (Z-IETD-FMK) on bacterial composition in fecal samples collected on day 0 and 12 from IL10−/− mice with colitis induced by AIEC/piroxicam." (PMID 36656595, 2023). "Eleven probiotic species have been genetically modified to produce therapeutic substances, including IL-10, antimicrobial peptides, antioxidant enzymes, and short-chain fatty acids, with potential therapeutic properties against colitis." (PMID 37049407, 2023). "FST treatment also promotes tissue repair and alleviates the severity of DSS colitis, TNBS colitis, and IL-10 gene deficiency-induced spontaneous colitis." (PMID 37391444, 2023). "First, IL‐10‐, and TLR5 knock‐out mice developed immune‐based colitis associated with increased mucus layer permeability, suggesting a link between mucus properties and the immune system." (PMID 37691494, 2023).
colitis (continued). "The probiotic C. Butyricum can promote the production of IL-10 by T cells and thus prevent the occurrence of colitis through an IL-10-dependent mechanism." (PMID 36902386, 2023). "Ye’s study found that IL-10-/- mice with higher abundance of Barnesiella developed lower levels of colitis disease." (PMID 37689643, 2023). "SCFAs enhance barrier integrity via the claudin-1 pathway, elevate IL-10 production through activating Treg differentiation, and improve the efficacy of broad antibiotic therapy in colitis." (PMID 37509556, 2023). "iNKT cell-primed Tregs produce IL-10 in the presence of bacterial diacylglycerols and show an enhanced suppressive capacity, which provides support for the iNKT-Treg axis in regulating colitis." (PMID 38274786, 2023). "In conclusion, in this study, we have demonstrated that MMTV virus is present in the IL-10−/− mouse model of colitis and contributes to severity of inflammation." (PMID 36869359, 2023). "The expression of IL-10 was reduced in colitis, and AAV2-miR-200a supplementation corrected the drop." (PMID 37646040, 2023). "IL-10 prevents colitis by eliminating dysfunctional mitochondria and inhibiting mTOR signaling and inflammatory vesicle activation in macrophages." (PMID 38029081, 2023). "Following the application of IMQ to the ear only, all mice survived the 4-week experimental period, following which IMQ-treated IL-10−/− mice had significantly more severe colitis than IMQ-treated DKO mice." (PMID 37717073, 2023). "Similar results were also found in a previous study in which depletion of gut obligate anaerobic microbes by clindamycin aggravated C jejuni-induced colitis in specific pathogen-free (SPF) IL10−/− mice by reducing intestinal DCA levels." (PMID 36755021, 2023). "B cells have been suggested to be involved in the immunoregulatory response to intestinal inflammation through the production of the anti-inflammatory cytokine IL-10 in T cell-induced colitis or DSS colitis models." (PMID 37849749, 2023). "Studies have shown that pentostatin can affect the release of pro-inflammatory factors and attenuate the effects of IL-10-/colitis." (PMID 37492574, 2023). "This bacterium was able to prevent colitis through inducing IL-10 (Interleukin-10) production in targeted intestinal epithelial CX3CR1+ macrophages." (PMID 37876938, 2023). "The inflammatory cytokines including TNF-α, IL-1β, IL-6, and IL-10 were higher in colitis mice than those in control mice (P < 0.01)." (PMID 36768559, 2023). "It was also confirmed that an S1PR1 agonist can inhibit apoptosis of epithelial cells and improve epithelial barrier function to reduce colitis in an IL-10-knockout colitis mouse model." (PMID 37560160, 2023). "IL-10−/− mice develop colitis shortly after weaning, which is highly dependent upon the environment the mice are raised in and the composition of their gut microbiome." (PMID 36869359, 2023). "In this study, we utilized the IL-10 knockout mouse model and induced colitis using dextran sulfate sodium (2%) after development." (PMID 37909786, 2023). "L. acidophilus strains NCFM and FAHWH11L56 improved DSS-induced colitis and increased levels of IL-10 and IL-17 in the colon by altering the CCL2/CCR2 and CCL3/CCR1 axes." (PMID 37485519, 2023). "The blockade of ανβ3 was found to reduce disease activity in the IL-10 knockout colitis model, suggesting that angiogenesis contributes to IBD pathogenesis." (PMID 36982601, 2023). "L. fermentum improved colitis, reduced TNF- α, IL-1β and IL-6 in serum and induced anti-inflammatory cytokine (IL-10) expression in the colons of DSS-induced colitis mice." (PMID 36986118, 2023). "Here, we measured the levels of fecal miR-21 before and during severe colitis and observed a significant increase specifically in female IL-10−/− mice." (PMID 37373511, 2023).
colitis (continued). "Altogether, the JAKinib tofacitinib, when provided not too early, is very efficient in limiting clinical signs of DSS-induced colitis and the expression of pro-inflammatory cytokines, while supporting Treg cells, IL-10 and IL-22 expression." (PMID 37275854, 2023). "One commonly utilized research model of IBD is the IL-10−/− mouse model of colitis, which not only resembles IBD but also responds to existing therapeutic options." (PMID 36869359, 2023). "To determine the requirement of Foxp3+ Treg-specific IL-10 for protection against colitis, we generated Foxp3-specific IL-10 knockout (KO) mice (IL-10 conditional KO [cKO] mice)." (PMID 37314833, 2023). "The expression of CRP, ESR, FC, interleukin-6(IL-6), IL-8 and IL-10 were different between the two groups, and except for IL-4 and IL-12P70, the expression of inflammatory markers was higher in extensive colitis." (PMID 37457023, 2023). "As noted in the methods, some Il10−/− mice in this cohort required early sacrifice as they exhibited poor health from colitis; we provide duplicate PCoA plots and average colitis histology score indicating harvest time post FMT." (PMID 38124090, 2023). "Previous studies have shown that all mouse models of colitis had bacteria in contact with epithelial cells, but IL-10−/− mice showed a thicker mucus layer than wild-type mice." (PMID 37111049, 2023). "Injection of OCH, a derivative of α-GalCer with Th2 selective activity, prevents DSS-induced colitis, which correlates with reduced Th1/Th2 cytokine ratios and increased IL-10 production." (PMID 38274786, 2023). "Here, we originally identified fundamental sex differences in the colitis phenotype of IL-10−/− mice." (PMID 37373511, 2023). "The IL10−/− colitis mouse model closely resembles that of individuals with inflammatory bowel disease (IBD), enhancing the model’s relevance to human disease." (PMID 37765299, 2023). "IMQ-treated IL-10−/− mice had significantly higher colitis scores than IMQ-treated DKO mice (P = 0.038)." (PMID 37717073, 2023). "While a few studies have used IL-10-KO mice to study the effects of certain mineral additives, isomaltodextrin supplementation, or high-fat diets on colitis, the use of this model for diet studies is still nascent." (PMID 37942948, 2023). "On the other hand, in ILCs-related colitis models such as CD40 colitis, IL-10 colitis, T-bet (-/-) Rag2 (-/-) ulcerative colitis (TRUC), GPR183 is one of the pathogenic mechanisms." (PMID 37720208, 2023). "It was shown that Tregs from individuals treated with butyrate showed increased secretion of IL-10 and adoptive transfer of butyrate-induced Tregs possess the ability to ameliorate colitis in mice." (PMID 38107848, 2023). "Recently, MadCAM-1 has been found to be critical for the recruitment of antibody-producing B cells into the intestinal mucosa in the IL-10-knockout colitis model." (PMID 36982601, 2023). "To confirm the impact of OJS on colitis, analgesia, and rewarding behavior, we utilized the IL-10 KO mouse model of spontaneous colitis." (PMID 37049400, 2023). "In another study, wogonin, a natural flavonoid, improved the therapeutic effects of MSCs on DSS-induced colitis in part via increasing IL-10 expression." (PMID 36707899, 2023). "A separate study showed that dopamine protected against indomethacin-induced colitis but that antagonizing D2 with sulpiride or domperidone blocked this effect, increasing IL-10 production and blocking indomethacin-induced intestinal hypermotility." (PMID 36757901, 2023). "As such, IL‐10 signaling is required for intestinal macrophages to prevent pro‐inflammatory exacerbation during DSS‐induced colitis through inhibition of mTOR signaling which controls macrophage pro‐inflammatory activity." (PMID 36795015, 2023). "The immune modulatory effect of valerate has been shown in experimental mouse models of colitis and multiple sclerosis, mediated by suppressing Th17 cells and the enhancement of IL-10 production." (PMID 37961441, 2023).
colitis (continued). "Harmful bacteria like Bacteroidetes and Proteobacteria producing TNF-α, IL-6, and IL-8 were found to increase, while beneficial bacterium like Firmicutes secreting IL-10 decrease in DSS-induced colitis mice." (PMID 37675045, 2023). "Oral gavage with L. curvatus isolated from cabbage reduced colitis pathogenesis and induced IL-10 production in bone marrow-derived dendritic cells (BMDCs)." (PMID 36986118, 2023). "Commensal products such as polysaccharide A condition DCs to induce IL-10 producing T regs which help in preventing colonic inflammation in the mouse colitis models." (PMID 37849749, 2023). "This piroxicam-accelerated colitis (PAC) model in IL-10−/− mice mimics several features of Crohn’s disease." (PMID 37189818, 2023). "We also found that the infusion of hUC-Exos and hFP-Exos regulated the level of IL-10 on mice with colitis." (PMID 36941715, 2023). "Mice with T-cell-specific deficiency of TGFβ signaling develop spontaneous colitis, in which we have demonstrated that helminth-induced regulation of colitis and generation of regulatory IL10 requires intact TGFβ circuitries." (PMID 37189818, 2023). "We found that one such model of spontaneous colitis, the interleukin (IL)-10 knockout (IL-10−/−) model derived from the SvEv mouse, had evidence of increased Mouse mammary tumor virus (MMTV) viral RNA expression compared to the SvEv wild type." (PMID 36869359, 2023). "Gallic acid has been shown to mediated colitis attenuation through the upregulation of hindgut acetate and butyrate, with elevated expression of IL-10 and TGF-β in newborn calves." (PMID 38149240, 2023). "Studies also revealed that continuous IL-10 administration in models of experimental colitis (IL-10-deficient mice, T cell transfer-induced mice colitis models, and DSS- and TNBS-induced colitis mice) can improve intestinal symptoms." (PMID 37554552, 2023). "In colitis mice, IL-10 potently suppresses the pro-IL-1β production transcriptionally in macrophages and its maturation to IL-1β, and alters Th17 cytokine dependency required for colitis pathogenesis." (PMID 37834058, 2023). "Treatment with an AhR ligand have been found to alleviate TNBS colitis by increasing the population of IL-10 secreting Tregs." (PMID 38107848, 2023). "To our knowledge, we have provided the first characterization of sex-based differences in the development of colitis in IL-10−/− mice." (PMID 37373511, 2023). "In this study, compared with L. lactis, oral administration of LL-IL-27 showed a stronger protective effect against CD4+CD45RBhi T-cell transfer-induced colitis by alleviating intestinal damage and promoting IL-10 expression in the colon." (PMID 37049407, 2023). "Recently, a previous study found that miR-31 KO mice developed more severe colitis as evidenced by increased numbers of leukocytes and macrophages, elevated levels of pro-inflammatory cytokines, as well as decreased levels of IL-10 after DSS treatment." (PMID 37048492, 2023). "The best-known model is the IL-10−/− knockout mouse, in which spontaneous colitis develops because of the inability of regulatory T (Treg) cells to produce IL-10." (PMID 36768278, 2023). "It is suggested to thrive in the inflamed colon of IL-10-/- knocked out mice, being sufficient to induce colitis and tumorigenesis through IL-6–STAT3 signaling." (PMID 37948383, 2023). "Consistently, colitis development and microbiota dysbiosis were also observed in 8‐week‐old Il10−/− mice." (PMID 36922750, 2023). "The surveillance of female and male IL-10−/− mice up to 17 weeks of age demonstrated that female IL-10−/− are more prone to severe colitis and dysbiosis." (PMID 37373511, 2023). "In this study, CD206+ M2 macrophages in the colon of sham-treated mice produced IL-10, and their number decreased with the onset of colitis." (PMID 38012544, 2023). "And Lactobacillus salivarius Ls33-purified peptidoglycan induces the dendritic cell to secrete IL-10 through a NOD2-dependent manner to relieve colitis." (PMID 37114045, 2023).